TRAF2 (TNF receptor associated factor 2)
Description:
E3 ubiquitin-protein ligase that regulates activation of NF-kappa-B and JNK and plays a central role in the regulation of cell survival and apoptosis. Catalyzes 'Lys-63'-linked ubiquitination of target proteins, such as BIRC3, IKBKE, MLST8, RIPK1 and TICAM1. Is an essential constituent of several E3 ubiquitin-protein ligase complexes, where it promotes the ubiquitination of target proteins by bringing them into contact with other E3 ubiquitin ligases. Regulates BIRC2 and BIRC3 protein levels by inhibiting their autoubiquitination and subsequent degradation; this does not depend on the TRAF2 RING-type zinc finger domain. Plays a role in mediating activation of NF-kappa-B by EIF2AK2/PKR. In complex with BIRC2 or BIRC3, promotes ubiquitination of IKBKE. Acts as a regulator of mTORC1 and mTORC2 assembly by mediating 'Lys-63'-linked ubiquitination of MLST8, thereby inhibiting formation of the mTORC2 complex, while facilitating assembly of the mTORC1 complex. Required for normal antibody isotype switching from IgM to IgG (By similarity).
Synonyms: TRAP3; RNF117; MGC:45012; TRAP
Tractability: Small molecule: it has a high-quality binding pocket. PROTAC: UniProt records ubiquitination sites on it; ubiquitination databases record sites on it; its protein half-life has been measured.
Target class: Enzyme; Transferase
Gene: Protein-coding gene on chromosome 9 (136,881,903 to 136,929,221, forward strand). Ensembl gene ENSG00000127191.
Subcellular location: Cytoplasm
Subcellular location (Human Protein Atlas): Cytosol
Pathways (Reactome):
Programmed Cell Death: CASP8 activity is inhibited; Caspase activation via Death Receptors in the presence of ligand; Dimerization of procaspase-8; RIPK1-mediated regulated necrosis; Regulation by c-FLIP; Regulation of necroptotic cell death
Immune System: Regulation of NF-kappa B signaling; TNF receptor superfamily (TNFSF) members mediating non-canonical NF-kB pathway; TNFR2 non-canonical NF-kB pathway; TRAF6 mediated IRF7 activation; TRAF6 mediated NF-kB activation
Signal Transduction: Regulation of TNFR1 signaling; TNF signaling; TNFR1-induced NF-kappa-B signaling pathway; TNFR1-induced proapoptotic signaling
Disease: Defective RIPK1-mediated regulated necrosis
Metabolism of proteins: Ub-specific processing proteases
Gene Ontology:
Molecular function: enzyme binding; identical protein binding; protein binding; protein kinase binding; protein phosphatase binding; protein-macromolecule adaptor activity; sphingolipid binding; thioesterase binding; tumor necrosis factor binding; tumor necrosis factor receptor binding; ubiquitin protein ligase activity; ubiquitin protein ligase binding; ubiquitin-protein transferase activity; CD40 receptor binding; signaling adaptor activity; metal ion binding; mitogen-activated protein kinase kinase kinase binding; protein-containing complex binding; tumor necrosis factor receptor superfamily binding; zinc ion binding
Biological process: CD27 signaling pathway; CD40 signaling pathway; non-canonical NF-kappaB signal transduction; positive regulation of canonical NF-kappaB signal transduction; positive regulation of extrinsic apoptotic signaling pathway; positive regulation of interleukin-2 production; positive regulation of JUN kinase activity; positive regulation of pyroptotic inflammatory response; positive regulation of T cell cytokine production; protein autoubiquitination; protein K63-linked ubiquitination; regulation of apoptotic process; regulation of protein-containing complex assembly; T cell activation; toll-like receptor signaling pathway; TORC1 complex assembly; TORC2 complex disassembly; tumor necrosis factor-mediated signaling pathway; extrinsic apoptotic signaling pathway via death domain receptors; inflammatory response; intrinsic apoptotic signaling pathway in response to DNA damage; intrinsic apoptotic signaling pathway in response to endoplasmic reticulum stress; protein-containing complex assembly; response to endoplasmic reticulum stress; signal transduction; and 11 more
Cellular component: cytoplasm; cytosol; IRE1-TRAF2-ASK1 complex; TRAF2-GSTP1 complex; tumor necrosis factor receptor superfamily complex; ubiquitin ligase complex; CD40 receptor complex; cytoplasmic side of plasma membrane; nucleoplasm; plasma membrane; cell cortex; membrane raft; protein-containing complex; receptor complex; vesicle membrane
Genetic constraint (gnomAD): Loss-of-function variants: 6 observed, 55.11 expected, observed/expected ratio (o/e) 0.11, 90% interval 0.059 to 0.22. The upper end of that interval is the gene's LOEUF score, 0.22, which puts it in group 1 of 6, group 1 being the genes least tolerant of losing a copy. Missense variants: 561 observed, 700.79 expected, observed/expected ratio (o/e) 0.8, 90% interval 0.75 to 0.86. Synonymous variants: 329 observed, 283.04 expected, observed/expected ratio (o/e) 1.16, 90% interval 1.06 to 1.27.
Homologues: Orthologues: chimpanzee TRAF2 (99% identical), macaque TRAF2 (98% identical), dog TRAF2 (91% identical), guinea pig TRAF2 (89% identical), pig TRAF2 (89% identical), mouse Traf2 (87% identical), rat Traf2 (86% identical), tropical clawed frog traf2 (67% identical), zebrafish traf2a (65% identical), zebrafish unm_sa808 (39% identical), Caenorhabditis elegans trf-1 (24% identical), Caenorhabditis elegans trf-2 (15% identical). Paralogues in human: TRAF5 (34% identical), TRAF3 (33% identical), TRAF1 (32% identical), TRAF4 (29% identical), TRAF6 (27% identical).
Diseases named in the same sentence as TRAF2 in open-access papers:
TRAF2 is named in the same sentence as 156 diseases in open-access papers, as found by Europe PMC text mining. Sharing a sentence is not in itself a finding about the gene and the disease. The quoted sentences say what the papers report.
breast carcinoma (34 papers, 2005 to 2025). "These are important observations since underlying mechanisms by which TRAF2, 4 and 6 individually or cooperatively regulate breast cancer cell behaviour are poorly understood and remain unexplored." (PMID 36944688, 2023). "Further validation of clinical data using a large study population with 183 metastatic breast cancer patients was used to examine the association between the expression of TRAF2/4/6 and tissue-specific metastatic potential of advanced breast cancer." (PMID 36944688, 2023). "In conclusion, our studies showed that the TRAF2/IKK/NFκB axis in osteotropic breast cancer cells contributes to breast cancer associated osteolytic bone damage." (PMID 29311633, 2018). "To test if TRAF2 is implicated in the regulation of osteolytic activity of breast cancer cells, we assessed skeletal tumour growth and osteolysis in mice after intra-tibial injection of the osteotropic sub-clone MDA-231-BT." (PMID 29311633, 2018). "Here, we carried out in vitro functional studies to examine the effects of knockdown and overexpression of cancer-specific TRAF2 on osteoclast and osteoblast changes associated with breast cancer." (PMID 29311633, 2018). "We also confirmed that cancer-specific expression of TRAF2 regulates mammary tumour growth and showed for the first time that TRAF2 is implicated in skeletal tumour burden." (PMID 29311633, 2018). "TRAF2 overexpression has been documented in tumor samples from certain types of cancer such as human pancreatic cancer, breast cancer and gastric cancer, and is associated with cancer progression, metastasis, and shorter patient survival." (PMID 28482915, 2017). "Furthermore, TRAF6 and TRAF2 have also been found to be enriched in an additional 15 pro-inflammatory and immuno-modulatory pathways and processes implicated in breast cancer tumorigenesis and metastasis." (PMID 36944688, 2023). "Similarly, TRAF2 expression was also found to be associated with distant metastasis-free survival in breast cancer patients." (PMID 36944688, 2023). "Whilst these findings indicate that TRAF6 is an important regulator of breast cancer tumorigenesis and metastasis, accumulating evidence from studies in advanced breast cancer patients suggests that the expression of TRAF2 and 4 is associated with poor survival rates." (PMID 36944688, 2023). "In view of this, we hypothesized that TRAF2 is implicated in bone metastasis, skeletal tumour growth and osteolysis associated with advanced breast cancer." (PMID 29311633, 2018). "Tumour necrosis factor receptor associated factor 2 (TRAF2), a key component of NFκB signalling, has been identified as an oncogene, but its role in the regulation of breast cancer osteolytic metastasis remains unknown." (PMID 29311633, 2018). "In addition, TRAF2 regulates the activity of various breast cancer oncogenes, and inhibition of TRAF2 has been associated with reduction in mammary tumour growth." (PMID 29311633, 2018). "Thus, the TRAF2/NFκB axis is implicated in the regulation of skeletal tumour burden and osteolysis associated with advanced breast cancer." (PMID 29311633, 2018). "Thus, therapeutic targeting of TRAF2/NFκB signalling may be of value in protecting the skeleton from osteolytic bone damage associated with advanced breast cancer." (PMID 29311633, 2018). "In breast carcinoma cells, miR-205 upregulation specifically targets TRAF2, leading to significant downregulation of both TRAF2 mRNA and protein expression levels." (PMID 41001034, 2025). "In breast cancer, the overexpression of TRAF2 enhances the malignant migration of tumor cells and the formation of osteoclasts, thereby facilitating the osteolytic metastasis of breast cancer." (PMID 40573908, 2025). "In breast cancer, overexpression of TRAF2 enhanced malignant migration of tumor cells and osteoclast formation, thereby promoting breast cancer osteolytic metastasis." (PMID 37415241, 2023).
breast carcinoma (continued). "In stark contrast, the TRAF2 gene is highly amplified in samples from primary tumours (29%) compared to 18.8% in those from metastatic breast cancer patients." (PMID 36944688, 2023). "Our research identified 7 human studies that examined the association of TRAF2 (1 study), TRAF4 (3 studies), and TRAF6 (3 studies) with survival rate in breast cancer patients (719 patients)." (PMID 36944688, 2023). "To gain more insight into the mechanism(s) by which TRAF6, as well as TRAF2 and 4, influence the progression and metastasis of breast cancer, we conducted a KEGG pathway enrichment analysis." (PMID 36944688, 2023). "Perhaps most intriguing is the role of the TRAF2-NFκB connection in breast cancer cell transformation by the breast cancer oncogene IκB kinase ε (IKKε; IKKi)." (PMID 36011046, 2022). "In breast cancer, TRAF2 has been shown to be able to promote breast tumorigenesis, as well as its increased expression correlated with invasion and metastasis." (PMID 36009568, 2022). "IKKε-induced phosphorylation at Ser418 of CYLD decreased its activity and completely blocked CYLD-mediated deubiquitination of TRAF2, thereby promoting tumorigenesis in breast cancer cells." (PMID 34177595, 2021). "For example, IKBKE phosphorylates CYLD and TRAF2 in breast cancer cells, which induces NF-κB activation and contributes to cell transformation." (PMID 34544426, 2021). "Specifically, TRAF2 has suggested roles as an oncogene in epithelial cancer, osteotropic breast cancer and colon cancer, mainly through the NF-kB pathway." (PMID 33996849, 2021). "In the present study, we provide evidence to support the notion that cancer-specific TRAF2 contributes to breast cancer cell behavior in bone." (PMID 29311633, 2018). "Previous studies have shown that TRAF2-driven NFκB activation in breast cancer cells is primarily mediated by the expression and kinase activity of IKKβ and IKKε3,6,7,29." (PMID 29311633, 2018). "In the present study, we showed that cancer-specific TRAF2 expression contributes to breast cancer-induced osteolysis." (PMID 29311633, 2018). "Altogether, these results demonstrate that TRAF2 contributes to breast cancer related osteolysis through its regulation of both the canonical and non-canonical NFκB signalling pathway." (PMID 29311633, 2018). "The importance of caspase‐2 and TRAF2 for apoptosis induced by cisplatin, etoposide, and paclitaxel was also confirmed in the breast cancer cell line BT474 (Fig EV3B)." (PMID 29875129, 2018). "A number of studies have shown that TRAF2 oncogenic activity in parental breast cancer cells is driven by IKKβ and IKKε3,6,7,29,41." (PMID 29311633, 2018). "The TRAF2/NFκB signalling pathway plays a critical role in lactating mammary-gland development and breast cancer." (PMID 29311633, 2018). "The majority of studies thus far implicate the TRAF2/NFκB pathway in these processes were limited to the role of TRAF2 in mammary tumour growth." (PMID 29311633, 2018). "rs17243893 is an intronic SNP located in TRAF2, an oncogene which activates NF-κB in epithelial cancers including breast cancer, by activating the NIK-IKK complex." (PMID 26317411, 2015). "Recently, interaction between SphK2/S1P and histone deacetylases in breast cancer cells and S1P as a missing co-factor for E3 ubiquitin ligase TRAF2 in HEK 293 cells were shown." (PMID 21304987, 2011). "Very little is known on intracellular targets of S1P and recent reports indicate potential interaction between S1P and histone deacetylase 2 in breast cancer cells and S1P as a missing co-factor for E3 ubiquitin ligase TRAF2 in HEK 293 cells." (PMID 21304987, 2011). "Regarding TRAF2, somatic mutations in TRAF2 have been detected in diffuse large B-cell lymphoma; the knockdown of TRAF2 suppressed the proliferation of human breast carcinoma cells, and liquidambaric acid inhibited colon carcinoma cells by directly targeting TRAF2." (PMID 40142019, 2025).
breast carcinoma (continued). "Furthermore, findings from a number of in vitro and in vivo studies have shown that manipulation of TRAF2, 3 and/or 4 influences the behaviour of various breast cancer cells with different growth and metastatic abilities." (PMID 36944688, 2023). "Furthermore, there is evidence that certain microRNAs (miR-892b, miR-502-5p, miR-205-5p) downregulate TRAF2 expression and thereby suppress breast cancer development." (PMID 36011046, 2022). "Moreover, miR-502-5p reduces cell growth by downregulating the expression of TRAF2 in breast cancer cells." (PMID 34288816, 2021). "In addition, TRAF2 is upregulated in breast cancer, pancreatic cancer, and other malignant tumors and is significantly related to the prognosis of patients with prostate cancer." (PMID 33456463, 2020). "Moreover, dietary antioxidants, such as phenolics extracted from tartary buckwheat bran and astaxanthin, inhibited TRAF2 expression through their antioxidant effects in human breast cancer MDA-MB-231 cells and liver tissues of mice." (PMID 31835889, 2019). "TRAF2 overexpression also enhanced the ability of osteotropic breast cancer cells and their derived factors to induce osteoclast formation, inhibit osteoblast differentiation and to cause osteolysis by a mechanism that depends at least in part on NFκB activation." (PMID 29311633, 2018). "CHIP inhibits the NF-κB-mediated cell invasion via down-regulating TRAF2 in breast cancer." (PMID 29921293, 2018). "Our in vivo, ex vivo and in vitro investigation showed that TRAF2 expression in the osteotropic MDA-231 human breast cancer cells increases tumour cell growth in bone, and enhances the ability of these cells to induce osteoclast formation and to cause osteolysis in mice." (PMID 29311633, 2018). "Nonetheless, the contribution of TRAF2 to bone metastasis, skeletal tumour growth and osteolysis associated with advanced breast cancer has not been investigated." (PMID 29311633, 2018). "Elevated TRAF2 expression correlates with breast cancer cell invasion and metastasis in patients." (PMID 29311633, 2018). "However, the role of TRAF2 in the development of breast cancer bone metastasis and its contribution to osteoclast and osteoblast changes associated with these metastases has not been investigated." (PMID 29311633, 2018). "In breast cancer (BC), TRAF2 upregulation increased the migration of tumor cells and supported osteolytic metastasis by enhancing osteoclastogenesis." (PMID 40229245, 2025). "Thus, we hypothesise that agents that target multiple TRAFs, particularly TRAF2/4/6, can be of greater therapeutic value in the treatment of difficult-to-treat breast cancer subtypes." (PMID 36944688, 2023). "Notwithstanding, evidence from meta-analysis and bioinformatics validations indicates that TRAF2 and TRAF4 are highly expressed in primary and metastatic tumours, and their elevated level of expression is associated with metastasis and survival rate in breast cancer patients." (PMID 36944688, 2023). "Thus, it is reasonable to speculate that TRAF2 in osteotropic breast cancer cells orchestrates the expression of a set of tumour-derived factors that function cooperatively to alter the balance between osteoblasts and osteoclasts." (PMID 29311633, 2018). "Numerous studies have shown that the UPR can promote the proliferation of tumors such as liver cancer, melanoma, and breast cancer through various signaling cascades such as IRE1/XBP1/JNK, IRE1/XBP1/IL-6/STAT3, and IRE1/TRAF2/NF-κB." (PMID 39080273, 2024). "In MDA-MB-231 breast cancer cells, TRAF2 has been found to be a substrate for CHIP and that, consequently, CHIP regulates cell invasion via ubiquitination and degradation of TRAF2 and further inhibition of the NF-κB activation." (PMID 31130821, 2019). "Here, we report that stable overexpression of TRAF2 in parental and osteotropic sub-clones of human MDA-MB-231 (MDA-231) breast cancer cells increased cell growth and motility in vitro, whereas TRAF2 knockdown was inhibitory." (PMID 29311633, 2018).
breast carcinoma (continued). "Our present in vivo, ex vivo and in vitro investigation showed that TRAF2 overexpression in parental and osteotropic sub-clones of MDA-231 human breast cancer cells increased tumour cell growth and motility, whereas its knockdown is inhibitory." (PMID 29311633, 2018). "We took all of these parameters into account when evaluating the contribution of the previously defined breast cancer brain metastasis biomarkers (BCBrMBK): GRP94, TRAF2, FN14 and Inhibin." (PMID 26497551, 2015). "Based on these findings from pooled studies it is reasonable to conclude that therapeutic targeting of TRAF6, but not TRAF2 and 4, can be of value in the treatment of breast cancer." (PMID 36944688, 2023). "mean difference − 4.15, 95% CI − 6.06, − 2.24, Z score 4.25 (P < 0.0001)) is associated with significant reduction in tumour weight and volume in female rodents bearing the human triple-negative MDA-MB-231 (TRAF2, TRAF4 and TRAF6) and mouse 4T1 (TRAF6) breast cancer cells." (PMID 36944688, 2023). "There are five different fusions of the TRAF2 gene detected in human cancers, including TRAF2-CCDC183 in breast and bladder cancers, TRAF2-CACNA1B in bladder cancer, TMEM141-TRAF2 in breast cancer (TCGA), TRAF2-NOTCH1 in ovarian cancer and NTRK2-TRAF2 in melanoma." (PMID 30294322, 2018).